IL3 (interleukin 3)
Diseases named in the same sentence as IL3 in open-access papers (continued):
Sharing a sentence is not in itself a finding about the gene and the disease.
tumor (continued). "More importantly, IL-3 supports vessel formation and tumor angiogenesis, in vivo." (PMID 31014367, 2019). "Moreover, it has been shown that signals emanated by IL-3, released by tumor infiltrating T-cells, promote in vivo tumor expansion by increasing tumor neovascularization." (PMID 29238040, 2018). "However, the involvement of IL-3 in vascular cell proliferation and activation during physiological and tumor angiogenesis has been extensively documented." (PMID 29238040, 2018). "Moreover, ovarian and breast cancer-derived tumor infiltrating lymphocytes (CD25/CD4/CD5+TILs) express IL-3." (PMID 29238040, 2018). "Indeed, hematopoietic stem cells or progenitor cells require several growth factors, such as insulin, IL-3, IL-6, G-CSF and GM-CSF, but these are dispensable for the culture of tumor initiating cells." (PMID 24466252, 2014). "A previous study using a TRAMP-C1 tumor model further demonstrated that irradiation could change the IL-3-driven Th2 immune response to a Th1 immune response." (PMID 23441198, 2013). "For this purpose, we utilized an in vivo tumor model based on the IL-3 dependent cell line 32D." (PMID 24098520, 2013). "IL-3 is known to trigger anti-tumor responses and retard tumor growth in NSCLC after injections." (PMID 21935476, 2011). "To determine whether VEGFR-2 expression on pCSCs is regulated by tumor environmental cues, we examined the effects of cytokines on the expression in vitro., including Flt3 ligand (FL), GM-CSF, IL-3, IL-4, IL-6, IL-7 and IL-13." (PMID 18286204, 2008). "The question remains, whether IL-3 induced MDSC play a role for tumor development." (PMID 37275910, 2023). "In addition, IL-3 plays a role in regulating cell survival and the proliferation of tumor-derived endothelial cells (TEC) and increasing the expression of the AKT signaling pathway and pro-tumorigenic and angiogenic receptors, thereby controlling the tumor microenvironment." (PMID 37174125, 2023). "The immune cells that reside in the tumor microenvironment include lymphocytes, macrophages, and polymorphonucleocytes, many of which migrate into the tumor through the generation of tumoral chemo-attractants such as CSF-1, IL-3, and VEGF and chemokines such as CCL-2." (PMID 35326557, 2022). "Moreover, since resistance to antiangiogenic treatments also relies on the occurrence of VM, the activation of the IL-3/IL-3Rα-mediated signalling may represent one of the rescue pathways granting tumour cell survival in this clinical scenario." (PMID 36010912, 2022). "For example, studies suggest that tumor-promoting Th2 cells exhibit high levels of IL-10 and TGF-β, whereas Th2 cells with elevated expression of IL-3, IL-5, and IL-13 demonstrate anti-tumor immunity." (PMID 40070825, 2025). "The attraction of MCs to a tumor requires the action of different chemokines produced by the tumor cells such as the stem cell factor (SCF), CXCL2, CCL2, CCL5, CCL11, CXCL12, CCL15, IL-3, and IL-33." (PMID 41465542, 2025). "Collectively, our data suggest that TME-derived signals, including IL-3 and M-CSF, induce CD163+ TAMs to proliferate within tumours as they differentiate from their monocytic precursors." (PMID 38903497, 2024). "The NSG-SGM3 mouse model expresses human cytokines IL-3, GM-CSF, and SCF, which can interact with human tumor cells and murine cells, potentially affecting immune microenvironment." (PMID 39768223, 2024). "For example, studies have suggested that tumor-promoting Th2 cells have high levels of IL-10 and TGF-β, whereas Th2 cells with high expression of IL-3, IL-5, IL-13, and GM-CSF exhibit pro-inflammatory and anti-tumor immunity." (PMID 37332039, 2023). "Four of these cytokines (MCP-3/CCL7, PDGF-AB/BB, IL-13, and IL-3) showed significance in all analyses performed in our study (CMs vs. controls, GEP Class 2 vs. Class 1 CMs, and correlations with tumor dimensions)." (PMID 37509362, 2023).
tumor (continued). "GM-CSF, IL3, CSF2, and IL5 are important regulators of inflammation and immune suppression within the tumor microenvironment." (PMID 35574409, 2022). "Consistent with the TCGA molecular annotation, our data proved that the IL-3/IL-3Rα axis drives changes in EMT markers and acts as a booster of VM in vivo, translating into tumour cell homing and outgrowth in the lung." (PMID 36010912, 2022). "Myeloid differentiation and MDSC expansion are promoted by a variety of molecules, such as GM-CSF, M-CSF, IL-3, IL-6 and VEGF which are produced by tumor cells and the mechanisms used to recruit MDSCs in tumor-draining and distant LNs are described." (PMID 34241649, 2021). "In addition, it has been shown that an increased absolute platelet counts might reflect degree of the systemic inflammation induced by tumor, because pro-inflammatory mediators such as interleukin-2, interleukin-3, and interleukin-6 can stimulate the proliferation of platelet progenitor cells." (PMID 31921649, 2019). "Employing this approach, they recognized a core of nine cytokines that consistently correlated with efficacious tumour suppression: IL-12p70, IFN-γ, IL-1α, IL-1β, IL-2, IL-3, IL-6, CXCL10, and CXCL9." (PMID 29089667, 2017). "Here, we identify a novel mechanism by which IL-3 induces IKK activation which mediates mitogenic signaling in primary- and tumor mast cells and modulates the full biological response of IL-33." (PMID 25749030, 2015). "Cells obtained from an explanted tumor still expressed c-Kit, IL-3Rα, and IL-33R and showed IKK-dependent IL-3 production and proliferation." (PMID 25749030, 2015). "CD123, or the interleukin-3 (IL-3) receptor, has long been known as a potential target expressed on AML blasts, and a range of different approaches to targeting CD123 have been trialled with variable anti-tumour responses and toxicities observed." (PMID 40707180, 2025). "Furthermore, in the peripheral blood of 2208L tumor–bearing mice, IACS-70654 reduced the level of IL-3, a cytokine known to induce HSC and myeloid differentiation." (PMID 39287984, 2024). "Notably, our computational analysis of this high-dimensional data suggests that the key changes correlating with inhibition of tumor growth include the downregulation of CCL-2, CCL-7, CCL-12, and the upregulation of CXCL-10, CCL-24, CXCL-12 and IL-3." (PMID 38575562, 2024). "Notably, treatment-induced tumor volume reduction correlated with decreased levels of CCL-2, CCL-7, and CCL-12 and increased levels of CXCL-10, CCL-24, CXCL-12, and IL-3." (PMID 38575562, 2024). "Further, to assess whether SSFH/Cas9 inhibit by block IL-3/CD123 interaction and further interfere JAK2/STAT5 pathway, tumor tissues were collected and subjected to JAK2/STAT5 staining." (PMID 34121564, 2021). "In particular, IL3-exosomes loaded with imatinib statistically reduced the tumor burden when compared with IL3-exosomes without imatinib, normal exosomes loaded with imatinib, and imatinib alone (p < 0.0005) in a mouse model." (PMID 33540594, 2021). "SS30 could impair the function of CD123 molecule by competing with IL-3 to bind to CD123, and could down-regulate the expression of p-AKT and p-STAT5, resulting in inhibitory effect on CD123+ AML tumor cells in vitro and in vivo." (PMID 34121564, 2021). "Meanwhile, tumor immune-related pathways were also enriched, such as B cell development pathway, cd28 signaling in T Helper cell, chemokine signaling, IL-1 signaling, IL15 signaling, IL-2 signaling, IL-3 signaling, IL-4 signaling, and IL-8 signaling." (PMID 31258820, 2019).
tumor (continued). "This indicated that T cells have critical role on the tumor cure following HSV-sr39tk/GCV single therapy or combined with IL-3 therapy, but are not essential for IL-3 therapy alone." (PMID 23441198, 2013). "In tumors carrying the HSV-sr39tk gene (TRAMP-C1/sr39tk tumor), the iNOS-positive cells were mainly CD11b+ TAMs, but in tumors carrying IL-3 gene (TRAMP-C1/mIL3 tumor), the iNOS-positive cells were mainly CD11b− non-TAMs." (PMID 23441198, 2013). "Other factors that can affect engraftment of human tumor cells in mice include the presence of human cytokines, therefore NSG-SGM3, with transgenic expression of human IL3, GM-CSF and SCF, may also be used to expedite AML engraftment in our humanized murine model." (PMID 38289944, 2024). "It is worthwhile noting that a large panel of cytokines including MCP-1, M-CSF (CSF-1), IL-3, IL-10, IL-12, IL-16, MIP-1β, RANTES, TNF-α and TGF-β2 were upregulated resulting from autocrine effect in POSTN-overexpressing SKOV3 cells leading to potent enrichment of TAMs in the tumor microenvironment." (PMID 36550569, 2022). "IL-3, one of the most common inflammatory growth factors, can stimulate the proliferation and differentiation of myeloid elements, activate basophils to participate in the immune response, and inhibit angiogenesis by increasing TGF activity early in tumor formation." (PMID 35479514, 2022). "EV IL-3 failed to increase tumor cell number, its migration, or apoptotic rate." (PMID 33040091, 2020). "Furthermore, treatment with Imatinib-loaded IL3-EVs lead to dramatically prolonged survival times and reduced tumor burden compared to non-targeted EVs and free Imatinib." (PMID 31754377, 2019). "Likewise, four tumor‐derived EGFR variants W731R, P741S, N196D, and I938M also failed to drive the IL‐3‐independent growth of Ba/F3 cells." (PMID 31314158, 2019). "This discrepancy may be the result of a lack of suitable stimulating factors in the TRAMP-C1 tumor microenvironment, which was overcome when IL-3 was co-expressed." (PMID 23441198, 2013). "Since IL-3-transfected cells do not readily form tumor in vivo, twice the number of IL-3 expressing cells (TRAMP-C1/mIL3 and TRAMP-C1/mIL3-sr39tk) were used compared to non-IL-3 expressing cells (TRAMP-C1 and TRAMP-C1/sr39tk) for all following in vivo experiments." (PMID 23441198, 2013). "It is likely IL-3 might have tumor promotion role when macrophages or T cells were absent in tumor microenvironment." (PMID 23441198, 2013). "An important role in the tumor microenvironment is held by platelets, which, by producing PDGF, may directly promote the growth of the tumor tissue; moreover, they produce a chain of proinflammatory cytokines (P-selectin, lL-1, IL-3, IL-3) and anti-inflammatory factors (TGF-β)." (PMID 35887947, 2022). "Therefore, our observations that, in tumour-bearing mice, the IL-3Rα-mediated signal blunted the “physiological” angiogenesis, boosted the VM, and increased the PD-L1 expression indicate that, as VEGF, IL-3 can “highjack” the TME, thereby contributing to tumour evasion." (PMID 36010912, 2022). "In hematologic malignancies, IL3-Lamp2B–engineered exosomes loaded with imatinib or BCR-ABL siRNA selectively targeted chronic myeloid leukemia cells, reducing tumour burden without overt systemic toxicity." (PMID 41181109, 2025). "Carrageenan treatment did not affect the tumor growth of examined tumor cell lines in the absence of GCV, but reduced the therapeutic effects of HSV-sr39tk/GCV applied both individually and in combination with IL-3." (PMID 23441198, 2013).
infection (112 papers, 2006 to 2025). The state of being infected such as from the introduction of a foreign agent such as serum, vaccine, antigenic substance or organism. "Infection was also associated with rising levels of IgE and the MC-activating type-2 cytokines interleukin (IL)-3, -4, -5, -9, -10 and -13 as well as increased intestinal permeability and bacteremia through 10 days PI." (PMID 35154114, 2022). "Some larvae subjected to Ss-DAF-12 knockdown developed to iL3 and were able to infect a susceptible host but exhibited low reproductive potential and shortened duration of infection compared to controls." (PMID 31929961, 2019). "Bone marrow stem cells from these animals were immortalized by infection with virus encoding constitutively expressed HoxA9 or Nup98-HoxA9, in the continuous presence of IL-3 and GM-CSF." (PMID 24177192, 2013). "This is the first study to report an association between IL3, malignancy, and risk of infection." (PMID 29051761, 2017). "Furthermore, inhibition of autophagy was shown to increase susceptibility of cells to various stimuli including interleukin-3 (IL-3) deprivation, starvation and infection." (PMID 18266953, 2008). "B-1 cells are producers of a variety of molecules, such as IL-10, IL-3, and GM-CSF, which are capable of exerting influence on other cell populations and thus may influence the susceptibility or resistance in models of infection." (PMID 31338088, 2019). "To further probe the basis for the MC cytokine response in LUVA cells, we performed RNA sequencing following 4 h of infection with S.Tmwt or S.Tm∆invG, as was done in our previous study on murine IL3‐BMMCs." (PMID 40838737, 2025). "In this study, we induced neutrophil differentiation from HSPCs in vitro by using cytokines produced by the host specially during infection and inflammatory conditions (IL-3 and G-CSF)." (PMID 40359412, 2025). "Previous studies have shown that the insulin signaling pathway is crucial for the development of iL3 in S. stercoralis during infection." (PMID 41406115, 2025). "After confirming successful infection via flow cytometry, the cells were deprived from IL-3 and monitored over the course of 14 days." (PMID 40647524, 2025). "G-CSF and interleukin-3 (IL-3) are two major growth factors that stimulate normal granulopoiesis and emergency granulopoiesis during infection." (PMID 38114747, 2024). "T helper 2 cells can produce cytokines, including IL-4, IL-5, IL-10, and IL-3,27 and the response of these cells plays a central role in protection against infection." (PMID 39807418, 2024). "More recent studies have also demonstrated the importance of basophils stimulated by IL-3 during infection." (PMID 39768136, 2024). "Conversely, infection significantly reduced levels of IL-1α, IL-2, IL-9, IL-10, IL-12 (p70), IL-13, IFNγ, IL-3, CCL4 (MIP-1β), CSF 2 (GM-CSF), CCL5 (RANTES), and TNFα." (PMID 37790429, 2023). "hCsf2/Il3 DKI mice exhibited ~103-fold increased lung CFUs 24 h after SPn14 infection alone, as compared with Rag2-/-Il2rg-/- controls." (PMID 37771584, 2023). "Taken together, these findings reveal that filarial DAF-12 are able to sense Δ4-dafachronic acid in host serum to resume iL3 development upon infection of the mammalian host." (PMID 37339136, 2023). "After the optimization of the infection scheme, it is very likely a small amount of iL3 can successfully infect M. meridianus because gerbils are the natural host of S. stercoralis, and their body size is nearly a hundred times smaller than that of beagles." (PMID 38003750, 2023). "A more persistent effect on cardiac fibrosis and systolic function at 35 days post-infection required the combined expression of IL9 with IL3, IL4, IL13, and IL15." (PMID 35508525, 2022). "The literature also pointed out that IL-2 and IL-3 appeared more obvious on the 4th day after infection, and they continued that way up to 14 days." (PMID 35878385, 2022).
infection (continued). "The pro-inflammatory cytokines IL-12p40 and TNF-α as well as the MC growth factor IL-3 were significantly increased in plasma of Mcpt4-/- mice compared to uninfected controls early after infection (4 days PI)." (PMID 35154114, 2022). "IL-3 is a glycoprotein cytokine involved in the hematopoietic response to infection, immune response and inflammatory stimulation." (PMID 36387880, 2022). "One possibility is that upon infection serum levels of cytokines such as GM-CSF, G-CSF, and IL-3 increase, which can promote myelopoiesis from progenitors." (PMID 33815375, 2021). "In another model of mucosal infection, we used intragastric infection with L. monocytogenes and 9 d following infection examined splenic T cells for Ag-specific production of IL-3 by intracellular cytokine staining." (PMID 31356170, 2019). "Based on these results, we propose a model in which IL-3 and GM-CSF secretion are superimposed on multiple T cell subsets when an infection is introduced at a barrier site such as skin or mucosal membranes." (PMID 31356170, 2019). "Pathogen-specific responses were also observed for IL-6 and GM-CSF, which were significantly reduced during chronic NT in cerebra of only T. canis-infected or T. cati-infected mice, respectively, while IL-3 and IL-9 were decreased in both infection groups." (PMID 31315623, 2019). "In our previous work, we have shown that IL-3–producing CD4+ T cells develop following vaccination with BCG by s.c. route or infection with M. tuberculosis by aerosol." (PMID 31356170, 2019). "While IL-3 and IL-9 were decreased in both infection groups, IL-6 was only significantly decreased in T. canis-infected and GM-CSF only in T. cati-infected mice." (PMID 31315623, 2019). "Collectively, these results suggest that generation of IL-3–secreting CD4+ T cells in vivo is restricted to infection or vaccination through barrier surfaces, such as skin and mucosa." (PMID 31356170, 2019). "GM-CSF and IL-3 promote emergency myelopoiesis (i.e., generation and differentiation of myeloid cells upon infection or in the context of inflammation) and also modulate effector functions of several innate immune cell subsets in vitro and in vivo." (PMID 30769926, 2019). "Innate response activator (IRA) B cells are a subset of B1a-derived B cells that produces GM-CSF and IL-3 in infection and atherosclerosis models, thereby modulating myeloid cell differentiation and maturation." (PMID 30769926, 2019). "In contrast, two cytokines – TNF and IL3 – exhibited significantly higher levels in C57BL/6NJ mice on day 9 post-infection." (PMID 30713529, 2018). "Concomitant with the stromal breakdown after 14 days post infection, Il3, Gm-csf, and Scf expressions were significantly diminished on day 14 pi, followed by a decrease of Il7 gene expression on day 21 pi, but the factors were restored later during infection." (PMID 30619242, 2018). "One of the most notable is the introduction of non‐redundant cytokines (e.g. GM‐CSF, IL‐3), which has increased the efficiency and functionality of the innate immune cells and their response to infection." (PMID 29446074, 2018). "In our translational study, we found release of several key cytokines such as IL3 and 5 in response to PMA to be the most predictive of subsequent 3-month risk of infection with defined optimal cytokine values." (PMID 29051761, 2017). "Mitogen-stimulated release of IL3 and IL5 were significantly associated with increased risk for subsequent infection during maintenance therapy." (PMID 29051761, 2017). "We observed significant attenuation of ΔfmvB in pulmonary mouse infections and reduced levels of GM-CSF, IL-3, and IL-10 in the spleens of ΔfmvB-infected mice on day 5 post-infection, indicating that FmvB is involved in F. tularensis virulence." (PMID 27513341, 2016).